DYRK1A (dual specificity tyrosine phosphorylation regulated kinase 1A)
Diseases named in the same sentence as DYRK1A in open-access papers (continued):
Sharing a sentence is not in itself a finding about the gene and the disease.
Intellectual disability (49 papers, 2008 to 2025). "In this regard, intellectual disabilities, linked to hippocampal Dyrk1a overexpression, are ameliorated when Dyrk1a expression is reduced in DS mouse models." (PMID 40078964, 2025). "Dyrk1A deficiency is linked to various neurodevelopmental disorders, including developmental delays, intellectual disability (ID) and autism spectrum disorders (ASD)." (PMID 39633007, 2025). "On the other hand, haploinsufficiency of DYRK1A causes DYRK1A syndrome, a rare autosomal dominant disease characterized by intellectual disability, intrauterine growth retardation, microcephaly, and stunted growth." (PMID 39436397, 2024). "Alterations to DYRK1A have been consistently associated with cognitive functioning and neurodevelopmental disorders (e.g., autism, intellectual disability)." (PMID 39840013, 2024). "In a study with 14 individuals with de novo heterozygous variants of DYRK1A, all were reported to have congenital microcephaly, intellectual disability, developmental delay, and speech impairments, all of which are also sequelae of congenital CMV infection." (PMID 38932210, 2024). "DYRK1A syndrome is believed to account for up to 0.5% of individuals with intellectual disability, and studies have found that DYRK1A is one of the most frequent de novo mutated genes in ASD." (PMID 39308945, 2024). "DYRK1A is heavily implicated in neurodevelopmental disorders, with alterations in the DYRK1A gene frequently associated with intellectual disability." (PMID 37607329, 2023). "In contrast, in other intellectual disabilities, such as DYRK1A‐related haploinsufficiency syndrome with DYRK1A/1B mutations and/or deletions, downstream signalling is likely impaired in ways that are not yet well understood." (PMID 37607329, 2023). "DYRK1A loss-of-function mutations in heterozygosity cause a well-recognizable syndrome of intellectual disability and autism spectrum disorder." (PMID 36402907, 2022). "Decreased Dyrk1a expression is recognized as a cause of some autism spectrum disorders, as well as microcephaly and intellectual disability in different species." (PMID 34787650, 2022). "Inhibitory single nucleotide variants, small insertions/deletions or complete deletion of one DYRK1A-allele in patients or in mice also cause intellectual disability and other abnormalities, highlighting the sensitivity of DYRK1A-activity to gene dosage." (PMID 34983389, 2022). "DYRK1A mutations lead to syndromic form of autism and intellectual disability with many shared features." (PMID 33642997, 2021). "RHOA is a member of the RHO GTPase involved in several intellectual disabilities that affect dendritic structure in adult neurons, a phenotype also described in certain DS models or linked to DYRK1A." (PMID 33693642, 2021). "Munc18-1 is a proposed substrate for the Down Syndrome-related kinase dual-specificity tyrosine phosphorylation-regulate kinase 1a (Dyrk1a) and mutations in both genes cause intellectual disability." (PMID 32081899, 2020). "DYRK1A loss of function is also associated with neurodevelopmental defects, as DYRK1A haploinsufficiency in human leads to intellectual disability, microcephaly, growth and mental retardation." (PMID 30332747, 2018). "Patients with heterozygous truncation mutations or deletion of DYRK1A share a phenotype with microcephaly, intellectual disability, language delay, epileptic seizures, neonatal feeding problems, and facial dysmorphism." (PMID 29700199, 2018). "The present study describes the functional analysis of DYRK1A missense variants that were reported as pathogenic in patients with a syndromic form of autism and intellectual disability (MRD7)." (PMID 29700199, 2018). "Humans with de novo heterozygous variants of DYRK1A also have congenital microcephaly, structural brain abnormalities, and intellectual disability." (PMID 27844057, 2016).
Intellectual disability (continued). "More recently, point mutations in DYRK1A have been shown to be responsible for a recognizable syndrome characterized by microcephaly, developmental delay and intellectual disability (ID) as well as characteristic facial features." (PMID 26922654, 2016). "Chromosomal deletions encompassing DYRK1A have been associated with intellectual disability for several years." (PMID 26922654, 2016). "A protein-truncating mutation in the DYRK1A gene (Ile48LysfsX2) was reported in a human autistic individual with the following symptoms: 1) microcephaly, 2) intellectual disability, 3) anxiety, 4) ASD-related social deficits, 5) impaired speech, 6) stereotypic behavior, and 7) febrile seizures." (PMID 39633007, 2025). "Hence, the direct association between DYRK1A dosage imbalance and intellectual disability in T21 has been the focus of intense investigation for 40 years." (PMID 40519271, 2025). "Dysregulation of DYRKs have been reported in various neurodevelopmental phenotypes where haploinsufficiency of DYRK1A has been linked to the development of microcephaly, intellectual disabilities, and developmental delay, similar to clinical manifestations of congenital CMV3–5,31–33." (PMID 38504123, 2024). "Our data suggest that ADNP, CHD8, and DYRK1A groups may have separable and distinct phenotypes with regard to mental health, despite their shared associations with autism and intellectual disability." (PMID 38622540, 2024). "As follows, experimentations in mice having the expression of some genes increased or decreased allowed the highlighting of DYRK1A (dual specificity tyrosine phosphorylation-regulated kinase 1A) to be a candidate gene for intellectual deficiency, the most disabling phenotype in DS." (PMID 35631180, 2022). "In addition to autism, individuals with putative loss-of-function variants in DYRK1A exhibit microcephaly, intellectual disability, developmental delay and/or congenital anomalies of the kidney and urinary tract." (PMID 32467234, 2020). "Our study shows that overexpression of Dyrk1A causes broad abundance changes in the proteome and phosphoproteome of the hippocampus of transgenic mice, with most changes affecting proteins related to neuroplasticity and intellectual disabilities." (PMID 31803016, 2019). "Furthermore, Dyrk1a is upregulated in postmortem human brains, and high levels of Dyrk1a are associated with mental retardation." (PMID 28779511, 2017). "Several reports showed heterozygous mutations in DYRK1A in patients with multiple phenotypes, including developmental delays or intellectual disability with autism spectrum disorder, microcephaly, epileptic seizures, facial dysmorphisms and cardiac defects defining a new syndromic condition." (PMID 27375444, 2016). "The clinical importance of DYRK1A downregulation is supported by reports indicating that DYRK1A mutations are found in 0.1–0.5% of individuals with ASD and/or intellectual disability and ~0.5% of those with developmental disorders." (PMID 39633007, 2025). "It has been reported that haploinsufficiency of DYRK1A is related to intellectual disability (ID), autism spectrum disorder (ASD), intrauterine growth restriction (IUGR), and development delay (DD)." (PMID 38179410, 2023). "Amongst these triplicated genes, the Dyrk1a gene has been proposed as a major contributor to the intellectual disability and microcephaly in DS." (PMID 37841687, 2023). "More recently, DYRK1A haploinsufficiency has been proposed to cause a distinct syndrome, characterized by ASD along with microcephaly, intellectual disability, developmental delay, and/or congenital anomalies of the kidney and urinary tract." (PMID 32467234, 2020). "Among candidate genes explaining intellectual disabilities in DS people, the dual specificity tyrosine-phosphorylation-regulated kinase 1A, DYRK1A, is located in the DS chromosome 21 critical region." (PMID 30115750, 2018).
Intellectual disability (continued). "Pathogenic de novo mutations in the DYRK1A gene were identified in 19 of 4293 patients in the Deciphering Developmental Disorder (DDD) Study and account for around 0.5% of syndromic intellectual disability in this cohort." (PMID 29700199, 2018). "The most statistically significant association with candidate genes, AGA, DYRK1A, SETD4, and TTC3, was found in mental retardation (adjP = 0.0014)." (PMID 29739397, 2018). "DYRK1A haploinsufficiency results in a common phenotypic profile including intellectual disability, speech and motor difficulties, microcephaly, feeding difficulties, and vision abnormalities." (PMID 29034068, 2017). "A growing number of case reports with DYRK1A haploinsufficiency exhibit common phenotypic features including microcephaly, intellectual disability, speech delay, and facial dysmorphisms." (PMID 29034068, 2017). "DYRK1A haploinsufficiency was initially identified for its role in intellectual disability, which is clinically defined as childhood onset of significant cognitive and adaptive impairment." (PMID 29034068, 2017). "Mutation of DYRK1A was strongly linked to a subset of ASD patients with seizures at infancy, hypertonia, intellectual disability, microencephaly, dysmorphic facial features and impaired speech." (PMID 28702161, 2017). "Haploinsufficiency of DYRK1A is responsible for a syndrome characterized by intellectual disability (ID), microcephaly and dysmorphic features (MIM 614104)." (PMID 26922654, 2016). "DYRK1A testing should be considered in individuals with the facial features, intellectual disability and post-natal microcephaly." (PMID 26922654, 2016). "Once diagnosed with DYRK1A-related intellectual disability, a cardiac and ophthalmologic assessment would be recommended as would routine surveillance by a pediatrician for psychomotor development, growth, and feeding." (PMID 26922654, 2016). "Recently, disruption of DYRK1A has been found in Autosomal Dominant Mental Retardation 7 (MRD7), resulting in severe mental deficiency." (PMID 27375444, 2016). "Major steps have been achieved to establish the role of DYRK1A in intellectual disabilities such as DS and MRD7 syndromic condition involving heterozygous loss-of-function mutations affecting DYRK1A." (PMID 27375444, 2016). "In particular, mental retardation, which is a characteristic symptom of DS, is thought to be related primarily to the DYRK1A gene in the DSCR." (PMID 27483355, 2016). "For example, de novo mutations in the dual-specificity tyrosine-(Y)-phosphorylation-regulated kinase 1 A (DYRK1A) gene are associated with a type of syndromic ASD and intellectual disability that presents with microcephaly." (PMID 26483618, 2015). "The chromosomal location of human DYRK1A, along with the phenotypic defects observed in the Dyrk1A+/− mutant mice that carry one copy of the murine homologue, suggest that DYRK1A might be a good candidate gene for some of the cases of partial monosomy 21 linked to mental retardation." (PMID 18648535, 2008). "The present report investigates the intrinsic ability of Dyrk1A+/− mice to form spatial memories, a function that is disturbed in patients with mental retardation and relies on particular weakness in hippocampal functions." (PMID 18648535, 2008). "Of note, most individuals with variants in DDX3X, KAT6A, and DYRK1A have moderate‐to‐severe intellectual disability and do not typically use verbal speech to communicate." (PMID 39846212, 2025). "Despite shared associations with autism and intellectual disability, disruptive variants in ADNP, CHD8, and DYRK1A may yield variable psychiatric phenotypes among children and adolescents." (PMID 38622540, 2024). "Like those with DYRK1A haploinsufficiency, individuals with DS often present with intellectual disability, along with craniofacial abnormalities, and musculoskeletal deficits, potentially due to the roles of DYRK1A in bone formation, osteoclastogenesis, neurogenesis, and synaptogenesis." (PMID 39308945, 2024).
Intellectual disability (continued). "Haploinsufficiency of the DYRK1A gene, due to various truncation mutations, microdeletions, or missense variants resulting in reduced DYRK1A, is responsible for MRD7, an autism spectrum disorder displaying microcephaly, intellectual disability, speech impairment, and distinct facies (reviews:)." (PMID 34205123, 2021). "Dyrk1a levels are tightly regulated, as both overexpression and lack of Dyrk1a activity are associated with mental retardation." (PMID 28779511, 2017). "This study of the DYRK1A haploinsufficiency phenotype, compiling previously published and newly identified cases, confirms a phenotype characterized by microcephaly, intellectual disability, speech delay, motor difficulties, feeding difficulties, and vision abnormalities." (PMID 29034068, 2017). "Despite shared associations with autism and intellectual disability, data presented here suggest ADNP, CHD8, and DYRK1A may yield variable psychiatric phenotypes among affected children and adolescents, including differential associations with early development." (PMID 38622540, 2024). "Furthermore, DYRK1A phosphorylates several neurodegenerative diseases associated proteins, such as APP and α-synuclein, and has been associated with intellectual disability and targeted to improve cognitive performance in subjects with DS (without AD) and other intellectual disabilities." (PMID 35630721, 2022). "DYRK1A is affected in 21q22 microdeletion in human, and is associated with growth retardation, primary microcephaly, facial dysmorphism, seizures, ataxic gait, absent speech and intellectual disability." (PMID 33642997, 2021). "Considering the intellectual disability associated with DYRK1A haploinsufficiency, a passive, noninvasive neuroimaging approach may help illuminate neuroendophenotypes that link the behavioral phenotype to the underlying neural mechanisms." (PMID 29034068, 2017). "Although most research has focussed on DYRK1A, there is also a recent report of DYRK1B haploinsufficiency in a family with mild and severe intellectual disability, seizures, autism, obesity, and other symptoms." (PMID 37607329, 2023). "Finally, the significant effects obtained relative to DYRK1A and BACE1/C99 represent promising observations in searching for new molecules for ameliorating intellectual disability and fighting AD development in DS." (PMID 36670973, 2023). "Meanwhile, recent human genetic studies found that reduced (not increased) DYRK1A expression is associated with various neurodevelopmental brain dysfunctions, including developmental delay, microcephaly, autism spectrum disorder (ASD), intellectual disability, and seizures." (PMID 39633007, 2025).
microcephaly (45 papers, 2008 to 2025). A congenital or acquired developmental disorder in which the circumference of the head is smaller than normal for the person's age and sex. "Since mutations in DYRK1A are associated with stunted growth and microcephaly, we wondered if neuronal cells require DYRK1A to maintain proper cell size." (PMID 39436397, 2024). "In DYRK1A syndrome, the loss of one copy of DYRK1A leads to stunted growth and microcephaly in humans." (PMID 39436397, 2024). "Loss of function mutations in DYRK1A that lead to decreased DYRK1A protein levels result in primary microcephaly and developmental delays, reminiscent of mnb mutant phenotypes." (PMID 39271109, 2024). "This concept should be approached carefully, as constitutional DYRK1A haploinsufficiency causes microcephaly." (PMID 37451904, 2023). "Of note, DYRK1A haploinsufficiency in D-CRO1-Δ1 and D-CRO1-Δ5 organoids did result in these two lines producing smaller organoids than T-CRO1, underpinning the clinical reports of DYRK1A haploinsufficiency causing microcephaly." (PMID 37451904, 2023). "DYRK1A gene truncation and a heterozygous DYRK1A genotype—known as DYRK1A haploinsufficiency syndrome, is associated with microcephaly, speech delay, dysmorphia, and autistic features." (PMID 37808474, 2023). "Gene dosage is critical, as heterozygous Dyrk1a+/− mice are viable but have microcephaly, reduced body weight in adults, and motor deficiencies." (PMID 37607329, 2023). "Loss-of-function mutations in the DYRK1A gene, located on human chromosome 21 (Hsa21,) lead to an intellectual disability syndrome associated with microcephaly, epilepsy, and autistic troubles." (PMID 34587162, 2021). "We suggest the CXADR gene is involved with developmental delay in patients with 21q21.1 microduplication and we provide additional evidence that DYRK1A is associated with microcephaly and scoliosis in patients with a 21q22 microdeletion." (PMID 31061677, 2018). "One patient with 21q22.13 microdeletion of DYRK1A shows association with microcephaly and scoliosis." (PMID 31061677, 2018). "Previous studies showed an association between DYRK1A and microcephaly had been well established and around half of the patients also displayed scoliosis." (PMID 31061677, 2018). "Single Nucleotide Variances and small INDELs on this genes also demonstrate similar phenotype of microdeletion on 21q22.13 that reaffirms this strong association between DYRK1A gene and syndrome with microcephaly and scoliosis." (PMID 31061677, 2018). "In Drosophila models, truncating mutations to DYRK1A (Drosophila ortholog termed the Minibrain (Mnb) gene) result in microcephaly, including intact but smaller brain structures." (PMID 29034068, 2017). "In human or mouse, hemizygous loss of DYRK1A leads to microcephaly, a severe disorder of brain development." (PMID 28884684, 2017). "Humans heterozygous for loss or mutation of DYRK1A display severe microcephaly, but also commonly show developmental delay and intrauterine growth retardation." (PMID 28884684, 2017). "DYRK1A mutations cause autosomal dominant mental retardation type 7, in which microcephaly is an important clinical finding." (PMID 26846091, 2016). "Other genes are strongly associated with epilepsy and ID (e.g., CHD2 and DYRK1A), often with very specific clinical manifestations (e.g., microcephaly and late-onset epilepsy in the case of patients with DYRK1A variants." (PMID 26917491, 2016). "In humans, DYRK1A haploinsufficiency is associated with microcephaly, growth and mental retardation." (PMID 24375627, 2014). "Variants in DYRK1A may lead to DYRK1A syndrome that includes both neurological and skeletal phenotypes, including short stature, microcephaly and tibial osteochondrosis." (PMID 39136051, 2024). "DYRK1A mutation in humans is connected to intellectual impediments, microcephaly, and ASD." (PMID 36129935, 2022).